BAALC (BAALC binder of MAP3K1 and KLF4)
Diseases named in the same sentence as BAALC in open-access papers (continued):
Sharing a sentence is not in itself a finding about the gene and the disease.
melanoma (3 papers, 2008 to 2021). A malignant, usually aggressive tumor composed of atypical, neoplastic melanocytes. "Real time PCR analyses with RNA from melanoma cell lines (n = 30) confirmed the BRAF-activation dependent up-regulation of BAALC." (PMID 18631381, 2008). "The BRAFV600E dependent expression of a newly identified potential effector gene, BAALC (brain and acute leukaemia, cytoplasmatic) was confirmed by real time PCR analyses in complimentary experiments in melanoma cell lines." (PMID 18631381, 2008).
chronic myeloid leukemia (1 paper, 2025). "Although the BCAT1::BAALC fusion has not been previously reported, both BCAT1 and BAALC are associated with chronic myeloid leukemia." (PMID 40242470, 2025).
meningioma (1 paper, 2020). A generally slow growing tumor attached to the dura mater. "While BAALC maps to chromosome band 8q22.3 and was initially identified in AML patients harboring a trisomy 8, MN1 is located on chromosome 22q12.3 and a transcription coactivator firstly described in meningioma pathogenesis." (PMID 32862286, 2020).
myeloid leukemia (1 paper, 2020). A clonal proliferation of myeloid cells and their precursors in the bone marrow, peripheral blood, and spleen. "Whereas the BAALC gene is studied regarding myeloid leukemia, its gene product, the BAALC protein, was neither characterized by biophysical nor biochemical methodology." (PMID 32240523, 2020).
cancer (7 papers, 2013 to 2025). A tumor composed of atypical neoplastic, often pleomorphic cells that invade other tissues. "Specifically, LRRC75A-AS1 has been shown to regulate miR-30a-5p through a sponge effect, resulting in increased BAALC expression, and contributing to cancer proliferation and invasion." (PMID 39575481, 2025). "In cancers like AML, BAALC expression levels are correlated with prognosis, with high expression indicating poor prognosis and lower patient survival." (PMID 41142795, 2025). "As the ability of cancer cells to grow without adhering to extracellular matrix (ECM) is associated with tumorigenicity in animal models, we next examined the effect of BAALC overexpression on anchorage-independent growth of MCF-7 cells." (PMID 33968759, 2021). "We confirmed the presence of numerous tumor-specific L1 insertions in these three cancer types and identify two potentially tumorigenic TE insertions, an Alu insertion in the enhancer region of the tumor suppressor gene CBL and an L1 insertion in the first exon of the BAALC gene." (PMID 27900322, 2016).
tumor (5 papers, 2016 to 2025). "In TNBC, SNHG22 drives tumor progression by sponging miR-324-3p and upregulating SUDS382; LRRC75A-AS1 (SNHG29) promotes tumor progression by targeting the miR-380-3p/BAALC pathway, and SNHG8 promotes tumor progression through the miR-335-5p/PYGO2 axis." (PMID 41301542, 2025). "Further, BAALC downregulation suppressed cell proliferation, invasion and EMT, but contributed to cell apoptosis in TNBC, suggesting the tumor-facilitating role of BAALC in TNBC." (PMID 32811810, 2020).
BAALC also shares sentences with these, for which no sentence is quoted: colorectal carcinoma (1 paper); congenital neutropenia (1); gastrointestinal stromal tumor (1); glioma (1); head and neck squamous cell carcinoma (1); hepatitis C infection (1); Hypertension (1); invasive breast carcinoma (1); liver fibrosis (1); Lymphadenopathy (1); lymphoid leukemia (1); metabolic syndrome (1); mucoepidermoid carcinoma (1); multiple myeloma (1); Pallor (1); purpura (1); Splenomegaly (1).